PYY2 (peptide YY 2 (pseudogene))
Gene: Transcribed unprocessed pseudogene on chromosome 17 (28,227,306 to 28,227,701, forward strand). Ensembl gene ENSG00000237575.
Subcellular location: Secreted
Diseases named in the same sentence as PYY2 in open-access papers:
PYY2 is named in the same sentence as 2 diseases in open-access papers, as found by Europe PMC text mining. Sharing a sentence is not in itself a finding about the gene and the disease.
PYY2 shares sentences with these, for which no sentence is quoted: asthma (1 paper); oral carcinoma (1).